MRPL19 (mitochondrial ribosomal protein L19)
Synonyms: L15mt; MRP-L15; L19mt; MRP-L19; KIAA0104; RPML15; RLX1; bL19m
Tractability: Small molecule: a structure with a bound ligand is known. PROTAC: ubiquitination databases record sites on it; its protein half-life has been measured.
Target class: Other cytosolic protein
Gene: Protein-coding gene on chromosome 2 (75,646,783 to 75,690,851, forward strand). Ensembl gene ENSG00000115364.
Subcellular location: Mitochondrion
Subcellular location (Human Protein Atlas): Mitochondria
Pathways (Reactome):
Metabolism of proteins: Mitochondrial ribosome-associated quality control; Mitochondrial translation elongation; Mitochondrial translation initiation; Mitochondrial translation termination
Gene Ontology:
Molecular function: protein binding; structural constituent of ribosome
Biological process: mitochondrial translation; translation
Cellular component: mitochondrial large ribosomal subunit; mitochondrion; nucleus; mitochondrial inner membrane; ribosome
Genetic constraint (gnomAD): Loss-of-function variants: 27 observed, 27.13 expected, observed/expected ratio (o/e) 1, 90% interval 0.73 to 1.37. The synonymous counts are far from expectation, so gnomAD's model fits this gene poorly and the ratio says little. Missense variants: 341 observed, 301.07 expected, observed/expected ratio (o/e) 1.13, 90% interval 1.04 to 1.24. Synonymous variants: 139 observed, 108.74 expected, observed/expected ratio (o/e) 1.28, 90% interval 1.11 to 1.47.
Homologues: Orthologues: chimpanzee MRPL19 (99% identical), macaque MRPL19 (93% identical), pig MRPL19 (85% identical), dog MRPL19 (83% identical), rabbit MRPL19 (83% identical), mouse Mrpl19 (82% identical), rat Mrpl19 (81% identical), guinea pig MRPL19 (79% identical), tropical clawed frog mrpl19 (60% identical), zebrafish mrpl19 (59% identical), Drosophila melanogaster mRpL19 (40% identical), Caenorhabditis elegans mrpl-19 (36% identical).
Diseases named in the same sentence as MRPL19 in open-access papers:
MRPL19 is named in the same sentence as 19 diseases in open-access papers, as found by Europe PMC text mining. Sharing a sentence is not in itself a finding about the gene and the disease. The quoted sentences say what the papers report.
dyslexia (4 papers, 2011 to 2021). A learning disorder characterized by an impairment in processing written words. "The original study associating this locus with dyslexia showed an effect on gene expression of the co-regulated genes MRPL19 and C2ORF3, and differential expression across a set of brain regions." (PMID 23209710, 2012). "We analysed markers, previously reported to be associated with dyslexia, located within the MRPL19/C2ORF3, KIAA0319, DCDC2 and DYX1C1 genes in a sample of 520 individuals and tested them for association with reading and spelling measures." (PMID 20846247, 2011). "Moreover, the right temporoparietal region associated with rs1064395 in NCAN and also overlapped with a region previously associated with the dyslexia susceptibility genes KIAA0319, DYX1C1 and MRPL19, as well as CEP63." (PMID 34068951, 2021). "For instance, the European consortium NeuroDys performed a cross-linguistic case-control association study of dyslexia with data from more than 950 dyslexic individuals using targeted genotyping of selected markers in DYX1C1, DCDC2, KIAA0319, and the MRPL19/C2orf3 locus." (PMID 34068951, 2021).
endometrial cancer (3 papers, 2017 to 2020). Primary or metastatic malignant neoplasm involving the endometrium (mucous membrane that lines the endometrial cavity). "PSMC4, PUM1 and IPO8 were identified as the best reference genes combination for type 1 endometrial cancer (grades 1, 2 and 3), whereas for type 2 endometrial cancer (serous and carcinosarcoma), UBC, MRPL19, PGK1 and PPIA were the best reference genes combination." (PMID 32439920, 2020).
breast cancer (2 papers, 2007). A primary or metastatic malignant neoplasm involving the breast. "In a separate study, mitochondrial ribosomal protein L19 was one of six genes identified from microarray data obtained from different tissues and cells, as a good reference gene for real-time RT-qPCR experiments, when compared to conventional reference genes for mammary tumour expression profiling." (PMID 17651481, 2007).
breast tumor (1 paper, 2010). "The first dataset includes relative expression levels of 6 reference genes (ACTB, GAPDH, MRPL19, PSMC4, PUM1, and SF3A1) quantified in 80 breast tumor samples." (PMID 20470420, 2010).
endometriosis (1 paper, 2021). The growth of functional endometrial tissue in anatomic sites outside the uterine body. "Interestingly, we found the five most stable genes (EIF2B1, POP4, UBC, CASC3, and MRPL19) were not previously measured in endometriosis expression studies." (PMID 33686153, 2021).
ischaemic stroke (1 paper, 2020). "Moreover, mitochondrial ribosomal protein L19 (MRPL19) and MRPL51 were validated as OGDR resistance genes, indicating that they are important contributors and potential therapeutic targets for ischaemia‐reperfusion injury in ischaemic stroke." (PMID 32618081, 2020).
lung adenocarcinoma (1 paper, 2025). A carcinoma that arises from the lung and is characterized by the presence of malignant glandular epithelial cells. "For instance, Increased MRPL19 expression in lung adenocarcinoma was connected to lymph node metastasis." (PMID 40918472, 2025).
lung carcinoma (1 paper, 2025). "High expression of both MRPL19 mRNA and protein were associated with a poor prognosis in lung cancer patients." (PMID 39859078, 2025). "Similarly to MRPL15, upregulation of MRPL19 is observed in many types of cancer, including lung cancer, CRC, and gastric cancer." (PMID 39859078, 2025).
melanoma (1 paper, 2020). A malignant, usually aggressive tumor composed of atypical, neoplastic melanocytes. "We identified CLTA as the most robust reference gene for normalization of gene expression in primary melanomas followed by MRPL19 and ACTB, respectively." (PMID 31567589, 2020). "Based on our data, we recommend the use of a combined geometric mean of the expression levels of CLTA, MRPL19 and ACTB for normalization of gene expression in FFPE melanomas." (PMID 31567589, 2020). "We recommend using a geometric mean of the expression of CLTA, MRPL19 and ACTB for normalization of gene expression in melanomas and a geometric mean of the expression of CASC3 and RPS2 for normalization of gene expression in melanoma cell lines." (PMID 31567589, 2020).
meningioma (1 paper, 2011). A generally slow growing tumor attached to the dura mater. "Eight highest ranked reference genes (CASC3, EIF2B1, IPO8, MRPL19, PGK1, POP4, PPIA, and RPL37A) plus GAPDH and ACTB were then analyzed in 35 meningiomas, arachnoidea, dura mater and normal brain." (PMID 21806841, 2011).
cancer (3 papers, 2019 to 2024). A tumor composed of atypical neoplastic, often pleomorphic cells that invade other tissues. "In LUAD, MRPL19 has been suggested as a potential biomarker as it is associated with markers of cancer progression and metastasis." (PMID 39354291, 2024). "This suggests that the role of MRPL19 may be multifaceted, with different functions across a range of cancers." (PMID 39354291, 2024). "Likewise, for the other MRPLs that appear to have different functions between cancer types (e.g. MRPL19, MRPL37 and MRPL49)." (PMID 39354291, 2024).
tumour (3 papers, 2007 to 2010). "It is interesting to note that over-expression of MRPL19 does not associate with other molecular species to predict low levels of elastase, which in turn predicts a higher stage tumor." (PMID 19455237, 2007).
MRPL19 also shares sentences with these, for which no sentence is quoted: colorectal tumor (2 papers); brain cancer (1); carcinosarcoma (1); colon adenocarcinoma (1); diabetic macular edema (1); lymph node metastasis (1); neurological disease (1).